STK3 (serine/threonine kinase 3)
Description:
Stress-activated, pro-apoptotic kinase which, following caspase-cleavage, enters the nucleus and induces chromatin condensation followed by internucleosomal DNA fragmentation. Key component of the Hippo signaling pathway which plays a pivotal role in organ size control and tumor suppression by restricting proliferation and promoting apoptosis. The core of this pathway is composed of a kinase cascade wherein STK3/MST2 and STK4/MST1, in complex with its regulatory protein SAV1, phosphorylates and activates LATS1/2 in complex with its regulatory protein MOB1, which in turn phosphorylates and inactivates YAP1 oncoprotein and WWTR1/TAZ. Phosphorylation of YAP1 by LATS2 inhibits its translocation into the nucleus to regulate cellular genes important for cell proliferation, cell death, and cell migration. STK3/MST2 and STK4/MST1 are required to repress proliferation of mature hepatocytes, to prevent activation of facultative adult liver stem cells (oval cells), and to inhibit tumor formation. Phosphorylates NKX2-1 (By similarity). Phosphorylates NEK2 and plays a role in centrosome disjunction by regulating the localization of NEK2 to centrosome, and its ability to phosphorylate CROCC and CEP250. In conjunction with SAV1, activates the transcriptional activity of ESR1 through the modulation of its phosphorylation. Positively regulates RAF1 activation via suppression of the inhibitory phosphorylation of RAF1 on 'Ser-259'. Phosphorylates MOBKL1A and RASSF2. Phosphorylates MOBKL1B on 'Thr-74'. Acts cooperatively with MOBKL1B to activate STK38.
Synonyms: KRS1; MST2
Tractability: Small molecule: a structure with a bound ligand is known; a high-quality ligand is known; it belongs to a druggable protein family. PROTAC: UniProt records ubiquitination sites on it; ubiquitination databases record sites on it; its protein half-life has been measured; a small molecule that binds it is known.
Target class: Enzyme; Kinase; Protein Kinase; STE protein kinase STE20 family; STE protein kinase group; STE protein kinase MST subfamily
Gene: Protein-coding gene on chromosome 8 (98,371,228 to 98,942,827, reverse strand). Ensembl gene ENSG00000104375.
Subcellular location: Cytoplasm; Nucleus; Cytoplasm, cytoskeleton, microtubule organizing center, centrosome
Subcellular location (Human Protein Atlas): Intermediate filaments; Rods & Rings
Pathways (Reactome):
Signal Transduction: Signaling by Hippo
Gene Ontology:
Molecular function: ATP binding; identical protein binding; magnesium ion binding; protein binding; protein kinase activity; protein serine kinase activity; protein serine/threonine kinase activity; transcription regulator activator activity; protein serine/threonine kinase activator activity
Biological process: hippo signaling; intracellular signal transduction; negative regulation of canonical Wnt signaling pathway; negative regulation of cell growth involved in contact inhibition; positive regulation of hippo signaling; protein import into nucleus; protein localization to centrosome; protein phosphorylation; protein stabilization; apoptotic process; positive regulation of apoptotic process; regulation of MAPK cascade; negative regulation of growth; protein tetramerization; regulation of gene expression; signal transduction
Cellular component: centrosome; cytoplasm; nucleus; protein-containing complex; cytosol
Genetic constraint (gnomAD): Loss-of-function variants: 34 observed, 42.49 expected, observed/expected ratio (o/e) 0.8, 90% interval 0.61 to 1.07. The upper end of that interval is the gene's LOEUF score, 1.07, which puts it in group 4 of 6, group 1 being the genes least tolerant of losing a copy. Missense variants: 412 observed, 507.81 expected, observed/expected ratio (o/e) 0.81, 90% interval 0.75 to 0.88. Synonymous variants: 133 observed, 152.32 expected, observed/expected ratio (o/e) 0.87, 90% interval 0.76 to 1.01.
Homologues: Orthologues: dog STK3 (99% identical), rabbit STK3 (99% identical), chimpanzee STK3 (98% identical), pig STK3 (98% identical), macaque STK3 (98% identical), mouse Stk3 (97% identical), tropical clawed frog stk3 (93% identical), guinea pig STK3 (93% identical), rat Stk3 (89% identical), zebrafish stk3 (88% identical), Drosophila melanogaster hpo (60% identical), Caenorhabditis elegans cst-1 (54% identical), and 1 more. Paralogues in human: STK4 (78% identical), TNIK (41% identical), MAP4K4 (40% identical), MINK1 (38% identical), SLK (34% identical), STK10 (32% identical), STK24 (32% identical), STK26 (31% identical), NRK (31% identical), STK25 (31% identical), MAP4K3 (31% identical), TAOK3 (30% identical), and 23 more.
Diseases named in the same sentence as STK3 in open-access papers:
STK3 is named in the same sentence as 95 diseases in open-access papers, as found by Europe PMC text mining. Sharing a sentence is not in itself a finding about the gene and the disease. The quoted sentences say what the papers report.
breast carcinoma (11 papers, 2019 to 2025). "In prostate cancer, STK3 was regularly elevated and associated with decreased overall survival of patients and increased expression in breast cancer, which is correlated with worse patient outcomes." (PMID 40566602, 2025). "According to its canonical role, STK3 acts as a tumor suppressor, but STK3 is amplified and correlates with worse outcomes for breast cancer patients, suggesting that it plays a distinct role in breast cancer." (PMID 37345153, 2023). "In this study, we investigated Serine-Threonine Kinase 3 (STK3), a kinase in the Hippo Tumor-Suppressor Pathway, as a potential drug target to both inhibit breast cancer growth and mitigate chemotherapy-induced cardiotoxic damage." (PMID 37345153, 2023). "STK3 plays a role in inhibiting the progression of gastric cancer, hepatocellular carcinoma, and breast cancer by activating Hippo signaling." (PMID 33062724, 2020). "Recent studies demonstrate that STK3 acts as a tumor suppressor, restricting tumor size and metastasis in the hepatic cell cancer, pancreatic duct cancer, breast cancer, and colorectal cancer while exhibiting malignant potential in the gastric cancer and prostate cancer." (PMID 38436783, 2024). "Using genetic and pharmacological experiments in breast cancer and cardiomyocyte cell lines, we show that STK3 inhibition simultaneously slows breast cancer growth and invasion while providing protection to cardiomyocytes from doxorubicin-induced cardiotoxicity." (PMID 37345153, 2023). "Additionally, STK3 inhibits the proliferation of breast cancer cells and is overexpressed in breast cancer tissues." (PMID 33062724, 2020). "Likewise, in chromosome 8, arm-level gains of 8q and losses of 8p in human breast cancer SCNAs were further segmented into three amplification peaks involving STK3, MYC, and PTK2 and three deletion peaks involving CSMD1, PSD3, and IDO1 in hg19-aligned CMT SCNAs, respectively." (PMID 32680987, 2020). "Of note, STK3 and STK39 activation were reported in HER2-positive breast cancer cell lines after anti-HER2 blockade, suggesting these roles in resistance to anti-HER2 therapy." (PMID 35338158, 2022).
hepatocellular carcinoma (11 papers, 2012 to 2022). A malignant tumor that arises from hepatocytes. "Genetic deletion of STK3 in hepatocytes also led to the development of hepatocellular carcinoma." (PMID 33062724, 2020).
gastric cancer (10 papers, 2019 to 2025). A primary or metastatic malignant neoplasm involving the stomach. "CDH1-deficient gastric cancers exhibit high AKT serine/threonine kinase 3 (AKT3) expression, but specific drugs against this AKT isoform are not available." (PMID 35406381, 2022). "As another example, STK3 is overexpressed in gastric cancer, and its abundance predicts unfavorable clinical outcomes by driving cell cycle progression by activating the Ras-MAPK signaling pathway." (PMID 37345153, 2023). "It has been shown that STK3 promotes the tumorigenesis of gastric cancer by activating the cell cycle process mediated by Ras-MAPK." (PMID 36605099, 2022). "For instance, the reduced expression of STK3 was found in gastric cancer, and tumors from patients with lymph node metastasis showed minimal levels of STK3." (PMID 33062724, 2020). "On the other hand, high expression of STK3 was found in gastric cancer and might exert oncogenic function." (PMID 38215077, 2024). "STK3, by regulating the cell cycle, could accelerate the progression of gastric cancer and serve as a prognostic biomarker in GC23." (PMID 37031243, 2023). "Our objective is to elucidate the upregulation pattern and molecular mechanisms of STK3 in advancing gastric cancer (GC) progression." (PMID 40604818, 2025).
melanoma (10 papers, 2018 to 2025). A malignant, usually aggressive tumor composed of atypical, neoplastic melanocytes. "Furthermore, we noticed an increase in DUSP1 (Dual Specificity Phosphatase 1), STK3 (Serine/Threonine Kinase 3), ACTA2 (Actin, alpha 2, smooth muscle, aorta) and IL1A (Interleukin 1α) gene expression levels; however, the role of these genes in melanoma repopulation remains to be addressed." (PMID 31597943, 2019).
prostate carcinoma (9 papers, 2010 to 2025). A carcinoma that arises from epithelial cells of the prostate gland. "We present additional evidence for a role of STK3 in prostate cancer, as elevated STK3 gene expression was associated with more aggressive cancers and poorer clinical outcomes." (PMID 25707771, 2015). "The follow-up of this cohort established that gene amplification and mRNA upregulation of STK3 were strongly associated with a higher risk of prostate cancer recurrence (P = 0.026)." (PMID 25707771, 2015). "Together, rs7827435 A to T substitution might affect transcription factor binding, decrease STK3 mRNA expression, and reduce the risk of prostate cancer recurrence." (PMID 25707771, 2015). "We also reported that inhibition of STK3 genetically and with novel small-molecule inhibitors that we identified and validated slows prostate cancer growth and progression." (PMID 37345153, 2023). "PPARG is one of three members of the PPAR family of transcription factors that influence the function of serine/threonine kinase 3, which can lead to a more aggressive disease phenotype in prostate cancer." (PMID 34970420, 2021). "To further confirm the influence of STK3 on prostate cancer progression, we performed a comprehensive in silico evaluation of STK3 gene expression, DNA methylation, and gene copy number using publicly available The Cancer Genome Atlas (TCGA) datasets." (PMID 25707771, 2015). "However, recent studies have unmasked the oncogenic potential of STK3 in breast and prostate cancer progression." (PMID 40604818, 2025). "Other type of cancers such as prostate cancer and leukaemia showed increased expression of STK3." (PMID 38215077, 2024). "Therefore, MSTs, including STK3, exert a paradoxical and complicated effect during cancer development, and further investigations are warranted to uncover the mechanistic basis of the effect of the Hippo pathway genes on prostate cancer." (PMID 25707771, 2015). "The STK3/4 small-molecule inhibitor XMU-MP-1 displayed growth inhibition and reduced proliferation in prostate cancer cell lines." (PMID 40566602, 2025). "In fact, we have recently published that STK3 is frequently amplified in prostate cancer and has a noncanonical prostate cancer supportive role." (PMID 37345153, 2023). "In this regard, we recently reported that STK3, but not STK4, is amplified in prostate and BCa and expression is correlated with worse outcomes in patients with prostate cancer and BCa." (PMID 37345153, 2023). "We noted that many Hippo pathway SNPs (one in MST1, three in STK3, two in LATS2, one in MOB1B, and six in WWTR1; total 13 out of 75) genotyped in our prostate cancer patient cohort were not in Hardy-Weinberg equilibrium (HWE)." (PMID 25707771, 2015).
pancreatic cancer (5 papers, 2019 to 2025). "It is known that the overexpression of STK3 can reduce the proliferation, migration, and invasion of glioblastoma and pancreatic cancer." (PMID 33062724, 2020).
leukaemia (4 papers, 2020 to 2024). "In STK3-dependent leukemia, it was proposed that STK3 regulates cycle-dependent kinase 1 (CDK1) to drive cell proliferation." (PMID 37345153, 2023). "This potent inhibitor stands as a promising hippo target in leukaemia and MM cell lines expressing abnormal serine/threonine-protein kinases 3 (STK3/MST2) and 4 (STK4/MST1) expressions." (PMID 38927266, 2024).
lung cancer (4 papers, 2012 to 2024). A malignant neoplasm involving the lung. "In nonsmall cell lung cancer tissues, the overexpression of STK3 can reduce the invasion and metastasis ability of lung cancer cells and promote lung cancer cell apoptosis." (PMID 33062724, 2020).
Obesity (4 papers, 2022 to 2025). Accumulation of substantial excess body fat. "Canine and human STK3 levels were significantly overexpressed in the present study, which is important given that obesity is a risk factor for many cancers, including OSA." (PMID 40566602, 2025). "Of them, Ctnnd2, Dap, Marchf6, Cmbl, Sdc2, Cpq, Stk3, Vps13b, Cox6c, Grhl2, Fzd6, Cthrc1, Lrp12, and Zfpm2 showed associations or had functions related to atherosclerosis or obesity." (PMID 40362477, 2025). "Elevated levels of STK3 have been shown to correlate with obesity in humans, with pharmacological inhibition in mouse models showing improvements in metabolic profiles of these animals." (PMID 40566602, 2025). "Serine/threonine protein kinases 3 and 4 (STK3 and STK4), whose expression levels are upregulated in obesity, can promote mitophagy by regulating the phosphorylation and dimerization state of BNIP3." (PMID 37920803, 2023).
acute myeloid leukemia (2 papers, 2018 to 2023). Acute myeloid leukemia (AML) is a group of neoplasms arising from precursor cells committed to the myeloid cell-line differentiation. "In this regard, a subset of acute myeloid leukemias were also found to be dependent on STK3 signaling, and targeting STK3 in these subsets was beneficial." (PMID 37345153, 2023).
cervical carcinoma (2 papers, 2020 to 2022). A carcinoma arising from either the exocervical squamous epithelium or the endocervical glandular epithelium. "This suggests that the tumour suppressor activity of STK4/STK3 may be specific to HPV+ cervical cancer cells and warrants further investigation." (PMID 32555725, 2020). "Thus, overexpression of STK4/STK3 in HPV+ cervical cancer cells reconstitutes a functionally active Hippo signalling pathway capable of excluding YAP from the nucleus and reducing YAP-regulated gene expression." (PMID 32555725, 2020). "Thus, it was pertinent to investigate the consequences of re-activating Hippo signalling in cervical cancer cells by the re-introduction of STK4 or STK3." (PMID 32555725, 2020). "Together, these data show that Hippo re-activation results in a defect in cell proliferation and the ability of HeLa and CaSKi cells to form colonies in an anchorage dependent or independent manner, highlighting a potential tumour suppressor role for STK4/STK3 in HPV+ cervical cancer cells." (PMID 32555725, 2020).
colon cancer (2 papers, 2023). "Likewise, Hippo kinases LATS1 and LATS2, the immediate downstream phospho-targets of STK3/4, were also shown to be essential for tumor cell growth in a colon cancer." (PMID 37345153, 2023). "We believe that the STK3 and LATS1 genes among the SWH pathway factors show tumor suppressor properties in colon cancer cells since the decrease in their levels of gene expression is inter correlated." (PMID 36721804, 2023).
endometrial cancer (2 papers, 2022 to 2025). Primary or metastatic malignant neoplasm involving the endometrium (mucous membrane that lines the endometrial cavity). "The Cancer Genome Atlas (TCGA)’s study of Endometrial cancer patients showed frequently amplified in YAP/TAZ, WWTR1, and STK3." (PMID 36552980, 2022).
esophageal squamous cell carcinoma (2 papers, 2022 to 2024). Esophageal squamous cell carcinoma (ESCC) is a type of esophageal carcinoma (EC) that can affect any part of the esophagus, but is usually located in the upper or middle third. "Verifying the activation condition of STK3 in vitro is of great significance for the exploration of therapeutic approaches for esophageal squamous cell cancer." (PMID 38436783, 2024).
lung fibrosis (2 papers, 2023). "Anti-Phosphatidylinositol-5-phosphate 4-kinase type 2 beta (PIP4K2B)- and anti-AKT Serine/Threonine Kinase 3 (AKT3)-antibodies should be further explored to confirm their association with skin and lung fibrosis in SSc patients." (PMID 36982700, 2023). "We provide evidence that in response to bleomycin-induced pulmonary fibrosis, increased Taz through inactivation of Yap1, Stk3/4, or Nf2 is vital for AT1 cell differentiation and reduction of fibrosis." (PMID 37166104, 2023).
lymphopenia (2 papers, 2017 to 2018). Reduction in the number of lymphocytes. "In humans, studies have indicated that patients lacking STK4, which is a closely related paralog of STK3, showed T- and B-cell lymphopenia and recurrent bacterial and viral infections." (PMID 29226127, 2017).